USP38 (ubiquitin specific peptidase 38)
Diseases named in the same sentence as USP38 in open-access papers (continued):
Sharing a sentence is not in itself a finding about the gene and the disease.
gastric cancer (3 papers, 2024 to 2025). A primary or metastatic malignant neoplasm involving the stomach. "Based on data obtained from the GEPIA database, the researchers conducted a correlation analysis and found that USP38 is positively correlated with PD-L1 in gastric cancer." (PMID 40936898, 2025). "In gastric cancer, researchers found that USP38, similar to USP2 and USP14, also prevents FASN degradation by removing polyubiquitin chains from the amino acid sequence of FASN, with this process catalyzed by thiol groups." (PMID 40936898, 2025). "For instance, in esophageal squamous cell carcinoma, glioma, lung adenocarcinoma, and gastric cancer cell lines, knockdown of USP38 effectively inhibits tumor cell proliferation, while overexpression can reverse this process." (PMID 40936898, 2025). "In gastric cancer, analysis of the cancer genome atlas (TCGA) database reveals that USP38 is highly expressed in gastric cancer tissues compared to adjacent non-cancerous gastric tissues." (PMID 40936898, 2025). "In contrast, in gastric cancer and lung adenocarcinoma models, overexpression of USP38 promoted an increase in tumor volume and weight." (PMID 40936898, 2025). "USP38 enhances gastric cancer progression through deubiquitination and increases the stability of fatty acid synthase." (PMID 39605891, 2024). "Therefore, targeting FASN with USP38 inhibitors can be used as a potential treatment for gastric cancer patients with high expression of USP38." (PMID 39048965, 2024). "In addition, orilistat, an inhibitor of USP38, can reverse the phenotype of USP38 overexpressed gastric cancer cells." (PMID 39048965, 2024). "On the other hand, USP38 can deubiquitinate and stabilize FASN in gastric cancer, increasing triglyceride production and promoting growth and migration in gastric cancer cells." (PMID 39048965, 2024). "Additionally, since FASN has been shown to be an oncogenic protein, the regulation of FASN by USP38 may not be limited to gastric cancer." (PMID 40936898, 2025).
glioma (3 papers, 2021 to 2025). A benign or malignant brain and spinal cord tumor that arises from glial cells (astrocytes, oligodendrocytes, ependymal cells). "This tumor-suppressing function of USP38 makes it a potential novel target for targeted therapy in glioma." (PMID 40936898, 2025). "This characteristic makes USP38 a promising candidate for targeted cancer therapy, as the USP38/JAK2/STAT3 signaling axis regulation may be specific to certain malignancies, such as glioma." (PMID 40936898, 2025). "By analyzing the expression levels of DUBs and their correlation with GALM in gliomas, combined with in vitro experiments, four DUBs were selected, namely, USP18, TNFAIP3, USP39, and USP38." (PMID 35127693, 2021). "Among the most strongly decreased candidates, we observed proteins related to DNA repair (FANCA, USP38, NET1), autophagy (BCAS3), cancer cell migration and/or invasion (RASSF2, KMO, BCAS3), as well as proteins that can be generally considered as pro-tumorigenic, particularly in glioma (KMO, BCAS3)." (PMID 39833546, 2025).
cardiac hypertrophy (2 papers, 2024 to 2025). "There findings demonstrate that USP38 is associated with cardiac hypertrophy, which provides a promising therapeutic target for pathological cardiac remodeling." (PMID 38481817, 2024). "The TBK1 inhibitor Amlexanox significantly alleviates pressure overload induced-cardiac hypertrophy and myocardial fibrosis in mice with USP38 overexpression." (PMID 38481817, 2024). "Conversely, overexpression of USP38 accelerates the progression of cardiac hypertrophy and myocardial fibrosis." (PMID 38481817, 2024). "USP38 deletion significantly mitigates cardiomyocyte enlargement in vitro and hypertrophic effect induced by pressure overload, while overexpression of USP38 markedly aggravates cardiac hypertrophy and remodeling." (PMID 38481817, 2024). "Herein, we found that USP38 positively regulates pathological cardiac hypertrophy and remodeling by preventing the proteasomal degradation of p-TBK1, leading to the activation of Akt-GSK3β/mTOR signaling pathway and the acceleration of heart failure progression." (PMID 38481817, 2024). "Finally, our findings unveiled that USP38 deletion remarkably improves pressure overload-induced cardiac dysfunction, cardiac hypertrophy and myocardial fibrosis, accompanied by reduced the transcriptional level of hypertrophic and fibrotic markers, and vice versa." (PMID 38481817, 2024).
chronic kidney disease (2 papers, 2025). Impairment of the renal function secondary to chronic kidney damage persisting for three or more months. "In addition, USP38 has been identified as a critical mediator of chronic kidney disease (CKD)-associated AF." (PMID 41614876, 2025). "To investigate the upstream triggers of atrial USP38 upregulation in the setting of chronic kidney disease (CKD), we utilized a progressive 5/6 nephrectomy (5/6 Nx) mouse model." (PMID 40514673, 2025).
essential hypertension (2 papers, 2023 to 2024). Hypertension that presents without an identifiable cause. "In previous GWAS studies on blood pressure regulation, the association of ENPEP and KCNK3 with hypertension has been established, and the association between USP38 and blood pressure regulation still needs further validation." (PMID 36845374, 2023). "We used the eQTL information of all the tissues and finally identified three key genes associated with essential hypertension: ENPEP, USP38, and KCNK3." (PMID 36845374, 2023). "This gene-based association approach with tissue specificity has a lower multiple-testing burden and has identified three key genes in essential hypertension: potassium two-pore domain channel subfamily K member 3 (KCNK3), glutamyl aminopeptidase (ENPEP), and ubiquitin-specific peptidase 38 (USP38)." (PMID 38786976, 2024).
hepatocellular carcinoma (2 papers, 2025 to 2026). A malignant tumor that arises from hepatocytes. "This positive regulatory role suggests that USP38 may serve as a potential tumor biomarker involved in regulating tumor cell growth.However, current research on the USP38/Survivin signaling axis is limited to breast cancer and hepatocellular carcinoma." (PMID 40936898, 2025).
malaria (2 papers, 2015 to 2018). Malaria is a serious and sometimes fatal disease caused by a parasite that commonly infects a certain type of mosquito which feeds on humans. "The rs4266246 polymorphism (USP38, chromosome 4) was associated with pleiotropic protection from acidosis, severe malarial anemia, and severe malaria per se." (PMID 25805752, 2015). "In 32 loci passing quality control procedures, we found polymorphisms in USP38, FREM3, SDC1, DDC, and LOC727982 genes to be putatively associated with differential susceptibility to severe malaria." (PMID 25805752, 2015). "ABO blood group, USP38, FREM3 and alpha-thalassemia have previously been putatively associated with severe malaria in a Tanzanian population, but these associations are no longer statistically significant (P>10−4) at a more stringent GWAS significance threshold." (PMID 29381699, 2018).
Myocardial fibrosis (2 papers, 2023 to 2024). "Moreover, USP38-TG mice also displayed greater heart size, cardiomyocyte cross-sectional area and myocardial fibrosis than NTG mice under pressure overload stimulation." (PMID 38481817, 2024).
pulmonary fibrosis (2 papers, 2023 to 2024). Chronic progressive interstitial lung disorder characterized by the replacement of the lung tissue by connective tissue, leading to progressive dyspnea, respiratory failure, or right heart failure. "Their findings demonstrated that mice lacking USP38 displayed more severe pulmonary fibrosis and IL-33-associated lung inflammation following exposure to bleomycin, further solidifying the intricate connection between IL-33 and pulmonary fibrosis." (PMID 39301028, 2024).
Arrhythmia (1 paper, 2023). Any cardiac rhythm other than the normal sinus rhythm. "USP38 is dependent on the TAK1/NF-κB signaling pathway and regulates atrial inflammation, fibrosis, and arrhythmias after MI to some extent." (PMID 37953295, 2023).
Autoimmunity (1 paper, 2021). The occurrence of an immune reaction against the organism's own cells or tissues. "Interestingly, multiple deubiquitinating enzymes, such as USP3, USP38 or DUBA, negatively regulate type I IFN response, and dysfunction of the ubiquitin pathway has been previously linked to autoimmunity." (PMID 33573268, 2021).
cervical cancer (1 paper, 2018). A primary or metastatic malignant neoplasm involving the cervix. "By searching the Oncomime microarray database, we found that compared to its expression in normal tissue, USP38 is overexpressed in cervical cancer tissue (2.485-fold)." (PMID 30497519, 2018).
colon cancer (1 paper, 2018). "Furthermore, USP38 enhances the drug tolerance of human colon cancer cells." (PMID 30497519, 2018). "Therefore, USP38 is a deubiquitinase of LSD1 and regulates its functions in the human embryonic kidney cell line HEK293T and the colon cancer cell lines HCT116 and SW48." (PMID 30497519, 2018).
esophageal squamous cell carcinoma (1 paper, 2025). Esophageal squamous cell carcinoma (ESCC) is a type of esophageal carcinoma (EC) that can affect any part of the esophagus, but is usually located in the upper or middle third. "Related studies have found that in xenograft models of lung adenocarcinoma and esophageal squamous cell carcinoma, the tumor volume and size in the USP38 knockdown group were significantly smaller than in the control group." (PMID 40936898, 2025). "In esophageal squamous cell carcinoma, GEPIA database analysis shows that USP38 expression in esophageal squamous cell carcinoma (ESCC) tissues is significantly higher than in normal tissues, and its overexpression is significantly negatively correlated with relapse-free survival." (PMID 40936898, 2025).
heart failure (1 paper, 2024). Inability of the heart to pump blood at an adequate rate to meet tissue metabolic requirements. "Firstly, we found that the expression of USP38 is increased in heart tissues from patients of heart failure by microarray analysis, and of the top ten DEGs, the mRNA level of USP38 is most significantly upregulated in mouse heart tissues of heart failure." (PMID 38481817, 2024). "Together, we unveiled a novel role of USP38 in pressure overload induced cardiac remodeling and its potential as a therapeutic target for pathological cardiac remodeling and heart failure." (PMID 38481817, 2024). "Overall, USP38 overexpression aggravates pressure overload-induced pathological cardiac remodeling and promotes the development of heart failure." (PMID 38481817, 2024).
ischemic stroke (1 paper, 2019). A stroke disorder caused by obstruction of blood flow to the brain, due to thrombotic (local blood clot formation) or embolic (due to a blood clot or other material traveling from another site) event. "We identified four novel eGFR-associated loci which have been previously associated with ischemic stroke in other studies, specifically USP38, ZFHX3, PMF1-BGLAP, and TTBK151–53." (PMID 31451708, 2019).
leukemia (1 paper, 2019). A malignant (clonal) hematologic disorder, involving hematopoietic stem cells and characterized by the presence of primitive or atypical myeloid or lymphoid cells in the bone marrow and the blood. "However, USP38 levels did not change in TPA-treated HL-60 cells, indicating that USP3 and UPS35 were involved in leukemia cell differentiation." (PMID 31700696, 2019).
lung adenocarcinoma (1 paper, 2025). A carcinoma that arises from the lung and is characterized by the presence of malignant glandular epithelial cells. "Since the regulation of tumor-associated signaling pathways by KLF5 is USP38-dependent, USP38 becomes a potential therapeutic target for lung adenocarcinoma, providing a new direction for the precise treatment of lung adenocarcinoma." (PMID 40936898, 2025). "In lung adenocarcinoma, USP38 is abnormally overexpressed, and its elevated expression level is closely associated with lymph node metastasis and TNM staging." (PMID 40936898, 2025). "Similarly, in lung adenocarcinoma, USP38 also exerts deubiquitination activity on KLF5." (PMID 40936898, 2025).
non-small cell lung carcinoma (1 paper, 2025). A group of at least three distinct histological types of lung cancer, including non-small cell squamous cell carcinoma, adenocarcinoma, and large cell carcinoma. "In non-small cell lung cancer, USP38, upon binding with HIF-1α, removes the K11-linked polyubiquitin chains at Lys 769 of HIF-1α, preventing its proteasomal degradation and thereby maintaining the stability of the HIF-1α protein." (PMID 40936898, 2025). "Furthermore, according to existing research, USP38 has been shown to regulate the stability of HIF-1α protein in non-small cell lung cancer (NSCLC)." (PMID 40936898, 2025).
parathyroid cancers (1 paper, 2020). "Since loss of H2Bub has been reported in the pathogenesis of multiple cancers, including breast, colorectal, lung, and parathyroid cancers, the deubiquitinase USP38 might be a prominent epigenetic therapeutic target for inflammation, autoimmunity, and cancer in the future." (PMID 33240782, 2020).
schizophrenia (1 paper, 2025). A major psychotic disorder characterized by abnormalities in the perception or expression of reality. "Recently, the variant rs7681616-C present in the USP38 gene was associated with an increase in the risk of developing schizophrenia, suggesting the importance of this region in psychopathology." (PMID 40018685, 2025). "Another study identified that USP38 blood expression was significantly downregulated in schizophrenia patients compared to biological siblings and unaffected controls, aligning with our findings of decreased USP38 expression in individuals with increased externalizing symptoms." (PMID 40018685, 2025).
α-thalassemia (1 paper, 2015). "The new candidates accounted for the remaining 19.2% of the explainable variation, with USP38 (8.1%), DDC (3.8%), FREM3 (3.0%), SDC1 (2.6%), and LOC727982 (1.7%) all accounting for more variation than ABO blood group and α-thalassemia but in aggregate less than the sickle HbAS polymorphism." (PMID 25805752, 2015).
cancer (8 papers, 2018 to 2026). A tumor composed of atypical neoplastic, often pleomorphic cells that invade other tissues. "In cancer screening, detecting USP38 expression levels can help assess a patient’s cancer risk." (PMID 40936898, 2025). "Silencing USP38 reduced the proliferation ability of OC cells and elevated the apoptosis rate of cancer cells." (PMID 41854204, 2026). "In different cancer cell lines, the expression of USP38 exerts different regulatory effects on tumor cell growth." (PMID 40936898, 2025). "We detail the structural characteristics of USP38, its differential expression patterns across cancer types, and its impact on key cellular processes including proliferation, migration, invasion, and apoptosis." (PMID 40936898, 2025). "During tumor treatment, analyzing USP38 expression levels in cancer tissues can be used to evaluate the patient’s prognosis and inform the development of targeted treatment strategies." (PMID 40936898, 2025). "Within the context of malignant tumors, USP38 has emerged as a significant regulator, impacting fundamental biological processes including proliferation, migration, invasion, and therapeutic resistance via specific substrate targeting." (PMID 40936898, 2025). "In summary, this review synthesizes recent advancements delineating the complex regulatory landscape governed by USP38 in cancer." (PMID 40936898, 2025). "Taken together, our data demonstrated that HDAC3 is functional responsible for USP38 mediated histone modifications, which further controls the expression of cancer stem cell-related genes." (PMID 32404892, 2020). "Most importantly, the ubiquitination level of HDAC3 was responsible for USP38 mediated regulation of cancer stem cell-related transcripts." (PMID 32404892, 2020). "Since we found that USP38 suppressed mRNA levels of cancer stem cell related genes, we next analyzed the mRNA half-life of CD133, SOX2, and NANOG to gain further insights into USP38 mediated regulation of gene transcripts." (PMID 32404892, 2020). "Importantly, we demonstrated that the cellular level of USP38 regulates the histone modification status of these cancer stem cell-regulated genes." (PMID 32404892, 2020). "Because USP38 promoted the proliferation of cancer cells, we wanted to know whether it promotes the colony formation ability of cancer cells, which is related to cell proliferation and carcinogenesis." (PMID 30497519, 2018). "However, a unifying model for USP38’s role in cancer remains elusive." (PMID 40936898, 2025). "However, the role of USP38 in cancer is still under investigation." (PMID 32404892, 2020). "Mechanically, silencing USP38 decreased the expression level of PLK1 protein, repressing DDR in cancer cells." (PMID 41854204, 2026). "Deubiquitinase USP38 binds to PLK1 to stabilize PLK1 expression, facilitating DDR in OC cells and enhancing cancer cell proliferation, thereby reducing the apoptosis rate of cancer cells." (PMID 41854204, 2026). "Ubiquitin-Specific Protease 38 (USP38), a member of the deubiquitinating enzyme (DUB) family, exhibits a complex and context-dependent role in cancer progression." (PMID 40936898, 2025). "USP38 functions as a tumor suppressor through modulating the ubiquitination of HDAC3, which further controls the expression of cancer stem cell-related genes." (PMID 32404892, 2020). "Downregulation of USP38 led to ubiquitination of HDAC3, which resulted in decreased acetylation levels of H3K27 in the promoter regions of cancer stem cell related genes." (PMID 32404892, 2020). "Furthermore, USP38’s regulation of HDAC1 enzyme activity indirectly participates in the DNA damage repair process, providing new insights for clinical cancer treatment and prevention." (PMID 40936898, 2025). "Although preliminary data, such as the observed sensitization of HCT 116 cells to Oxal/5-FU upon USP38 overexpression, hint at its potential significance, systematic investigation across diverse cancer types and treatment modalities is largely absent." (PMID 40936898, 2025).